HRAS (HRas proto-oncogene, GTPase)
Description:
Signal transducer in the Ras-MAPK signaling pathway that regulates cell proliferation and survival. Ras proteins bind GDP/GTP and possess intrinsic GTPase activity. Recognized by LZTR1 that mediates its ubiquitination by a BCR (BTB-CUL3-RBX1) E3 ubiquitin-protein ligase complex.
Synonyms: HRAS1; C-BAS/HAS; C-H-RAS; C-HA-RAS1; CTLO; H-RASIDX; HAMSV; RASH1; p21ras
Tractability: Small molecule: a drug acting on it is in phase 2 or 3 trials; a structure with a bound ligand is known; a high-quality ligand is known; it has a high-quality binding pocket; it belongs to a druggable protein family. Antibody: its Gene Ontology location is reachable by antibodies, with high confidence; UniProt places it where antibodies can reach, with medium confidence. PROTAC: UniProt records ubiquitination sites on it; ubiquitination databases record sites on it; its protein half-life has been measured; a small molecule that binds it is known.
Target class: Other cytosolic protein
Chemical probes: CID-1067700
Gene: Protein-coding gene on chromosome 11 (532,242 to 537,343, reverse strand). Ensembl gene ENSG00000174775.
Subcellular location: Cell membrane; Golgi apparatus; Golgi apparatus membrane; Nucleus (Isoform 2); Cytoplasm; Cytoplasm, perinuclear region
Subcellular location (Human Protein Atlas): Cytosol; Basal body; Nucleoplasm
Pathways (Reactome):
Signal Transduction: Activated NTRK2 signals through FRS2 and FRS3; Activated NTRK2 signals through RAS; Activated NTRK3 signals through RAS; Downstream signal transduction; EGFR Transactivation by Gastrin; Erythropoietin activates RAS; Estrogen-stimulated signaling through PRKCZ; FRS-mediated FGFR1 signaling; FRS-mediated FGFR2 signaling; FRS-mediated FGFR3 signaling; FRS-mediated FGFR4 signaling; GRB2 events in EGFR signaling; GRB2 events in ERBB2 signaling; Insulin receptor signalling cascade; MAP2K and MAPK activation; MET activates RAS signaling; Negative regulation of MAPK pathway; PTK6 Regulates RHO GTPases, RAS GTPase and MAP kinases; RAF activation; RAF/MAP kinase cascade; RAS processing; Regulation of RAS by GAPs; SHC-mediated cascade:FGFR1; SHC-mediated cascade:FGFR2; SHC-mediated cascade:FGFR3; SHC-mediated cascade:FGFR4; SHC-related events triggered by IGF1R; SHC1 events in EGFR signaling; SHC1 events in ERBB2 signaling; SHC1 events in ERBB4 signaling; SOS-mediated signalling; Signaling by SCF-KIT; Signalling to RAS; VEGFR2 mediated cell proliferation; p38MAPK events
Disease: Constitutive Signaling by EGFRvIII; Constitutive Signaling by Ligand-Responsive EGFR Cancer Variants; Constitutive Signaling by Overexpressed ERBB2; Paradoxical activation of RAF signaling by kinase inactive BRAF; RAS signaling downstream of NF1 loss-of-function variants
and 28 more pathways
Gene Ontology:
Molecular function: GDP binding; GTP binding; GTPase activity; phospholipase C activator activity; protein binding; G protein activity; protein-membrane adaptor activity
Biological process: cellular response to gamma radiation; cellular senescence; negative regulation of cell population proliferation; negative regulation of gene expression; positive regulation of cell migration; positive regulation of cell population proliferation; positive regulation of epithelial cell proliferation; positive regulation of ERK1 and ERK2 cascade; positive regulation of JNK cascade; positive regulation of MAPK cascade; positive regulation of miRNA metabolic process; positive regulation of protein targeting to membrane; positive regulation of ruffle assembly; positive regulation of transcription by RNA polymerase II; positive regulation of wound healing; Ras protein signal transduction; regulation of actin cytoskeleton organization; regulation of cell cycle; regulation of cell population proliferation; regulation of neurotransmitter receptor localization to postsynaptic specialization membrane; regulation of transcription by RNA polymerase II; animal organ morphogenesis; cell surface receptor signaling pathway; chemotaxis; MAPK cascade; and 6 more
Cellular component: cytosol; glutamatergic synapse; Golgi apparatus; GTPase complex; nucleoplasm; plasma membrane; protein phosphatase type 1 complex; cytoplasm; endoplasmic reticulum membrane; Golgi membrane; membrane; nucleus; perinuclear region of cytoplasm
Genetic constraint (gnomAD): Loss-of-function variants: 11 observed, 20.39 expected, observed/expected ratio (o/e) 0.54, 90% interval 0.34 to 0.89. The synonymous counts are far from expectation, so gnomAD's model fits this gene poorly and the ratio says little. Missense variants: 204 observed, 269.62 expected, observed/expected ratio (o/e) 0.76, 90% interval 0.67 to 0.85. Synonymous variants: 149 observed, 111.45 expected, observed/expected ratio (o/e) 1.34, 90% interval 1.17 to 1.53.
Gene-disease validity (ClinGen):
ClinGen rates the evidence that HRAS causes each of these diseases.
Costello syndrome (autosomal dominant): Definitive. Costello syndrome (CS) is a rare multisystemic disorder characterized by failure to thrive, short stature, developmental delay or intellectual disability, joint laxity, soft skin, and distinctive facial features.
Noonan syndrome-like disorder with loose anagen hair (autosomal dominant): Disputed.
Cancer hallmarks: escaping programmed cell death (promotes); escaping immune response to cancer (suppresses); proliferative signalling (promotes); invasion and metastasis (promotes); genome instability and mutations (promotes); angiogenesis (promotes); angiogenesis; tumour promoting inflammation (promotes)
Homologues: Orthologues: chimpanzee HRAS (100% identical), macaque HRAS (100% identical), mouse Hras (100% identical), rat Hras (100% identical), guinea pig HRAS (99% identical), rat Hrasl1 (98% identical), zebrafish hrasa (95% identical), zebrafish hrasb (94% identical), dog HRAS (90% identical), tropical clawed frog hras (88% identical), pig HRAS (82% identical), zebrafish zgc:55558 (80% identical), and 3 more. Paralogues in human: KRAS (86% identical), NRAS (85% identical), RRAS2 (56% identical), RRAS (54% identical), RAP1B (52% identical), RAP1A (51% identical), MRAS (51% identical), RALA (50% identical), RALB (49% identical), RIT1 (48% identical), ERAS (47% identical), RAP2A (44% identical), and 23 more.
Diseases named in the same sentence as HRAS in open-access papers:
HRAS is named in the same sentence as 377 diseases in open-access papers, as found by Europe PMC text mining. Sharing a sentence is not in itself a finding about the gene and the disease. The quoted sentences say what the papers report.
breast cancer (131 papers, 1989 to 2025). A primary or metastatic malignant neoplasm involving the breast. "Increased expression and/or activation of HRAS is often associated with tumor aggressiveness in breast cancer." (PMID 34829731, 2021). "It has been reported that increased expression of HRAS is associated with more aggressive breast cancer tumors, while in another study, it was observed that HRAS mutations were rarely found in breast cancer tumors." (PMID 31979384, 2020). "HRAS, encoding GTPase HRAS (transforming protein p21), plays important oncogenic roles in multiple cancer types, including breast cancer." (PMID 32101536, 2020). "In the analysis for RFS, differential expression of ZNF611, ZNF304, RIPK1, DUSP8, TNFRSF21 and HRAS genes was associated with outcome for breast cancer patients who received radiotherapy." (PMID 30938061, 2019). "AT cells were transfected with a constitutively active HRAS gene, but these types of mutations are rare in human breast cancer, where specific genetic polymorphisms and higher expression levels are more prevalent." (PMID 30241319, 2018). "Our results demonstrate that adenomyoepitheliomas are genetically heterogeneous, and qualify mutations in HRAS, a gene whose mutations are vanishingly rare in common-type breast cancers, as likely drivers of ER-negative adenomyoepitheliomas." (PMID 29739933, 2018). "Somatic mutations in KRAS are common in gastric cancer tumors, NRAS is frequently mutated in melanoma, and HRAS to some extent in breast cancer." (PMID 30597917, 2018). "Among these three members, the mutation or aberrant expression of HRAS is most frequent in breast cancer." (PMID 27902470, 2017). "There is also evidence that breast cancer cell lines with a basal phenotype have a higher frequency of mutations in BRAF, KRAS, and HRAS than luminal breast cancer cell lines." (PMID 20604919, 2010). "Notably, only 6.5% of OSCC patients harbored at least one PIK3CA and HRAS mutation, whereas, these oncogenic mutations occur in 30-70% of solid tumours, including colorectal, ovarian, endometrial, lung, melanoma and breast cancer." (PMID 24224046, 2013). "However, the relationship between HRAS mutation with breast cancer treatment is still unclear." (PMID 27902470, 2017). "Knock-in or knock-out mice can be generated that either promote the expression of various oncogenes such as HRAS in breast cancer, or silence the effect of tumour-suppressor genes such as Brca1 in breast cancer, respectively." (PMID 36295541, 2022). "Among these genes are BUB1B and HRAS, which have previously been proven to play important roles in the biological behavior of breast cancer, and the other genes are all genes we fished out." (PMID 36428940, 2022). "First, for some recurrent mutations, such as those from CTNNB1, CSF1R, JAK2, HRAS, and RUNX1, an exhaustive literature search showed that the clinical significance in breast carcinoma has rarely been addressed." (PMID 34203389, 2021). "Here, we identified several statistically significant genetic interactions (e.g., BCL2L1 [P = 5.65x10-3], S6B Fig) for HRAS in breast cancer." (PMID 32101536, 2020). "Recent reports have shown that oncogenic and hormone-dependent transcription, in HRAS overexpressing cells and in breast cancer MCF7 cells respectively, leads to enhanced formation of R-loops and increased R-loop-dependent DNA damage during DNA replication." (PMID 32913330, 2020). "In contrast, entities such as breast cancer or HNC display a predominance of PIK3CA mutations (around 40%, for an overall mutation rate of KRAS, NRAS and HRAS inferior to 5% in both cases)." (PMID 28532501, 2017).
breast cancer (continued). "Since HRAS activation is very uncommon in human breast cancer the lingering question always remained on how useful were the chemically induced mammary cancers in rodents as models to study the molecular biology of human breast cancer." (PMID 27588403, 2016). "Recent recent studies have demonstrated that HRAS expression is sometimes a good prognostic factor in various cancer types, including breast cancer and neuroblastoma at the early stage." (PMID 26933804, 2016). "The MCF10A progression series of cell lines is a useful tool to study the process of tumor formation and metastatic progression driven by the HRAS oncogene, which is overexpressed in half of all breast cancers." (PMID 24086712, 2013). "Additionally, we discovered trans correlations between specific gene alterations (FANCA, HRAS, PIK3CA, MAP2K1, JAK2) and the expression of 22 proteins, suggesting potential molecular mechanisms underlying breast cancer development and progression." (PMID 39844043, 2025). "Previous works showed high expression of HRAS, KRAS, and NRAS in breast cancer compared with benign breast tissue; deletions of HRAS but no other mutations in RAS family members; and rare amplifications." (PMID 36358725, 2022). "The gene expression profile of basal-like breast cancer resembles that of tumors harboring RAS mutations and expression signatures of immortalized mammary cell lines expressing gain of function versions of HRAS or MEK1." (PMID 36358725, 2022). "Furthermore, Kaplan–Meier bioinformatics analyses indicated that the HRAS gene deregulation affected the overall survival rate of patients with breast cancer, leading to prognostic significance." (PMID 36358305, 2022). "This indicates that HRAS deregulation can serve as a prognostic marker for patients’ breast cancer." (PMID 36358305, 2022). "The results indicated that the HRAS gene deregulation might affect the overall survival rate of patients with breast cancer and thus affect prognosis significance." (PMID 36358305, 2022). "THSWD treatment of breast cancer may be related to targeting Ras, FoxO, PI3K-Akt, and other signal pathways associated with the core targets HRAS, MAPK1, AKT1, GRB2, and MAPK14." (PMID 34513708, 2021). "According to what found in other tumor types, KRAS confirms to be the most frequently mutated RAS isoform in breast cancer and its mutation, unlike mutations of HRAS and NRAS, is strongly associated with the poor clinical outcome." (PMID 31781501, 2019). "Furthermore, a large percentage of breast cancers were found to have measurable levels of mutations in critical genes of the MAP kinase pathway (i.e., KRAS, HRAS, and BRAF)." (PMID 30813596, 2019). "Finally, the use of OncoScantm has allowed us to detected mutations in five genes that have not been shown to be mutated in TCGA subset of Her-2 overexpressing breast cancer: CTNNB1, HRAS, KRAS, NF2 and SMARCB1." (PMID 28247034, 2017). "It was reported that breast cancer rarely possessed ERK pathway kinases mutations, BRAF (2%), KRAS (5%), and HRAS (1%) mutations occur at even lower frequency in TNBC, only a few of studies recognized breast cancer as a good candidate of ERK pathway targeting therapy." (PMID 29296238, 2017). "HRAS-G12V (prevalence 51%) is a common activating mutation in bladder cancer, and its role in breast cancer has not been described." (PMID 22185227, 2011). "We identified HRAS and PIK3CA mutations in the basal breast cancer cell lines SUM 159 and BT20." (PMID 20604919, 2010). "The haeme substrate 5-aminolevulinic acid (5-ALA) (200 mg kg−1) was administered to mouse strains that develop mammary tumours of various histological subtypes upon expression of the transgenic oncogenes HRAS, Polyoma Virus middle T antigen, or Simian Virus 40 large T antigen in the mammary gland." (PMID 16251872, 2005).
breast cancer (continued). "Several studies have revealed that ectopic expression of HRAS led to enhanced ability of cell migration, invasion, EMT and metastasis in breast cancer and colorectal cancer, suggesting that HRAS could be an important factor responsible for the progression of cancer 36,37." (PMID 32760207, 2020). "The applied human epithelial MCF10 breast cancer progression model compares the near‐diploid non‐malignant cell line MCF10A forming polarized spheroids with the tumorigenic invasively growing line MCF10CA, which bear activating mutations of HRAS and PIK3CA, and amplified MYC." (PMID 30104419, 2018). "HRAS mutation is not a common genetic alteration in human breast cancer, so the cell line series model might not accurately reflect the tumorigenic process in human breast cancers." (PMID 27512948, 2016). "Except for known disease proteins of breast cancer that found in the 6 protein complexes, many disease proteins that were associated with many other types of diseases could be found, with examples including E2F4, E2F5, HRAS, JUN, FOS." (PMID 24565064, 2014). "Breast cancer and SDC show similar expressions of several biomarkers, such as mammaglobin, GATA3, estrogen receptor (ER), HER-2, PI3KCA, and HRAS." (PMID 38539538, 2024). "And when we investigate if specific mutations were enriched in small or large tumors, we found only two genes, HRAS in small bladder cancer tumors and CDH1 in large breast cancer tumors." (PMID 39068253, 2024). "In breast cancer MDA-MB-468 cells, HRAS and NRAS were depleted, and in MDA-MB-231 cells, only NRAS was depleted." (PMID 38540084, 2024). "HRAS exon 5 inclusion was found to be anticorrelated with MYC activity across prostate and breast cancers." (PMID 37399401, 2023). "KRAS, NRAS and HRAS, referred to as oncogenic RAS, gained our attention from the viral carcinogenesis pathway, breast cancer pathway and renal cell carcinoma pathway." (PMID 35422066, 2022). "4T1 is a cell line derived from a spontaneous mammary tumor from BALB/c mouse and the MYC-HRAS MOSE are murine ovarian surface epithelial cells transformed by the introduction of mutant MYC and HRAS." (PMID 29348410, 2018). "Let-7 family miRNAs have been well-documented to target HRAS to regulate self-renewal and tumorigenicity and to sensitize KRAS mutant breast cancer to paclitaxel and gemcitabine." (PMID 27462780, 2016). "These chromosomes contain genes that are commonly involved in the invasion, metastasis and pathogenesis of breast cancer, including c-MYC on 8q24; HRAS, CD151, CTSD on 11p15; CCND1 on 11q13; and TOP2A on 17q21." (PMID 24456987, 2014). "For the first time, we have identified somatic mutations in genes related to the AKT/MAPK signaling pathways, such as EGFR, PIK3CA, KRAS, HRAS and NRAS, in brain metastases of breast cancer and other types of cancer." (PMID 20604919, 2010). "Interestingly, 38 and 44% decreases in the levels of the farnesylated and acylated NRAS were observed in the two breast cancer cell lines, MDA-MB-231, and MDA-MB-468, respectively, while HRAS levels showed a 36% decrease only in MDA-MB-468 cells." (PMID 36961909, 2023). "We found that the vast majority of IGF regulators were upregulated in various cancers, such as HRAS and YWHAZ in lung squamous cell carcinoma (LUSC), SHC1 in kidney cancer, PRKCZ in bladder cancer (BLCA) and in breast cancer (BRCA), and NCK2 in cholangiocarcinoma (CHOL)." (PMID 35935986, 2022).